APOA1 (apolipoprotein A1)
Diseases named in the same sentence as APOA1 in open-access papers (continued):
Sharing a sentence is not in itself a finding about the gene and the disease.
Obesity (continued). "In addition, proteomic pathway analyses highlighted other proteins involved in lipoprotein metabolism (APOA1, BMP1, FABP3 and ANGPTL4) that are key markers in obesity and NAFLD." (PMID 36678141, 2023). "Numerous experimental results explained how ApoA1 may lose its functionality in many inflammatory and pathological conditions, including T2DM, liver diseases, obesity and COVID-19." (PMID 35327501, 2022). "It has been established that obesity itself alters HDL metabolism (particularly apoA-1), and it may be that the presence of anti-apoA-1 antibodies augments this derangement and therefore enhances CVD risk." (PMID 34888742, 2022). "Our results also showed positive associations between the ApoB/ApoA1 ratio and ALT and AST regardless of age and obesity, which is consistent with previous reports." (PMID 35069437, 2021). "In our study, the ApoB/ApoA1 ratio was significantly correlated with WC, TG, HDL, SBP, and FPG, but not with DBP, and the association was independent of age or obesity." (PMID 35069437, 2021). "The effect of obesity on HDL and APOA1 levels could be modulated by lipid and glucose metabolism from dietary consumption." (PMID 32120838, 2020). "The findings underscore the profound impact of obesity and glycemic status on insulin resistance and lipid abnormalities while also suggesting that APOA1 genotype may not independently influence these metabolic outcomes within obese subgroups." (PMID 41422312, 2025). "ApoA1 was significantly and negatively associated with T2DM in women without obesity." (PMID 35327501, 2022). "ApoA1 was significantly and negatively associated with T2DM in women with or without obesity." (PMID 35327501, 2022). "However, as for ApoA1, serum haptoglobin variability observed in T2DM, obesity, and COVID-19 could also be directly due to the intestine, such as changes in endothelial permeability." (PMID 35327501, 2022). "Circulating apolipoprotein A1 (P = 0.009), HDL cholesterol (HDL-C) (P < 0.0001), cholesterol efflux (P = 0.002) and paroxonase-1 (PON-1) activity (P < 0.0001) were lower, and serum amyloid A (SAA) (P < 0.0001) was higher in participants with obesity compared to controls." (PMID 34131170, 2021). "The SNPs of ABCA-1 (LDL-C and ApoA1/ApoB); LIPC (TC, LDL-C, ApoA1 and ApoB); LIPG (ApoB); MTHFR (TC, TG and LDL-C); MYLIP (TC and TG); PCSK9 (TG, HDL-C, ApoB and ApoA1/ApoB); PPARD (TG and ApoA1/ApoB); and SCARB1 (TG, ApoA1 and ApoB) interacted with overweight/obesity to modulate serum lipid levels." (PMID 23039238, 2012). "In the NAFLD-Biopsy subset, for subjects with T2DM, with or without obesity, all characteristics were different vs. subjects without T2DM and non-obese (controls), except for ApoA1 level and NASH prevalence." (PMID 35327501, 2022). "Therefore, our findings were not surprising as FTO may interact with ApoA1 in regulating weight, TBW, and SLM and thus affects obesity and also corroborate studies showing SNPs from ApoA1 associated with lower levels of HDL as obesity risk factors." (PMID 32076432, 2019).
myocardial infarction (112 papers, 2007 to 2026). Gross necrosis of the myocardium, as a result of interruption of the blood supply to the area, as in coronary thrombosis. "Plasma concentration of apoB and the apoB/apoA1 ratio have been reported to strongly relate to increased risk of fatal myocardial infarction in both men and women." (PMID 40129271, 2025). "Based on a large international case–control study (INTERHEART) spanning 52 countries, the ApoB:ApoA1 ratio was shown to be a better marker for heart attack risk than the traditional TC:HDL-C ratio." (PMID 40944180, 2025). "Specifically, we aim to investigate the relationship between prothrombotic gene variants, APOA1 rs5069 polymorphism, and early myocardial infarction." (PMID 39295604, 2024). "Serum levels of ApoA1 in healthy patients are ∼1.5 g/L in healthy volunteers and slightly lower in those at risk for myocardial infarction, ∼1.25 g/L, and in the same groups, the ApoB levels were 1.08 g/L and 1.18 g/L, respectively." (PMID 38479648, 2024). "In a sub-study of the ARISTOTLE trial, higher levels of Apolipoprotein A1 were independently associated with a lower composite risk of ischaemic stroke, systemic embolism, myocardial infarction, and cardiovascular mortality." (PMID 33483737, 2022). "When analysed separately, Apolipoprotein A1 was found to be a risk factor for each of the individual outcomes apart from myocardial infarction." (PMID 33483737, 2022). "The apoB to apoA1 ratio has been suggested as superior to traditional risk markers in a case–control study of acute myocardial infarction comprising >20.000 participants." (PMID 36501072, 2022). "Although NM-Yaqui children showed lower OB prevalence than NM-urban children, NM-Yaquis presented the highest prevalence of low ApoA1 (17.8%), one of the best predictors of myocardial infarction and a clear sign of cardiovascular risk." (PMID 34886385, 2021). "Both ApoB/ApoA1 ratios were considered a better risk predictor to acute myocardial infarction than the TC/HDLc ratio." (PMID 33725226, 2021). "Elevated apolipoprotein B (apoB) and elevated apoB/apoA-1 ratio increase the risk of myocardial infarction (MI) and stroke, whereas high apoA-1 is protective." (PMID 34851955, 2021). "We and others have shown that both apoB and apoA-1, and the balance of these apolipoproteins, expressed as the apoB/apoA-1 ratio, are strongly associated with myocardial infarction (MI) and stroke." (PMID 34851955, 2021). "A positive, independent association was seen between anti-apoA-1 IgG and a history of myocardial infarction (β = 0.103, p = 0.026) and primary glomerular disease (β = 0.116, p = 0.016)." (PMID 31261925, 2019). "Serum ApoB/ApoA1 ratio was also reportedly associated with first myocardial infarction." (PMID 35842724, 2022). "Similarly, another study found APOA1 polymorphisms (75 G/A and +83 C/T) as a risk for myocardial infarction in a North Indian population." (PMID 34440141, 2021). "Some mutations of APOA1 have been associated with increased risk of myocardial infarction, and another one, Apo A1-Milano, may reduce the risk." (PMID 28342064, 2017). "A pilot study found that APOA1 polymorphisms (−75 G/A and +83 C/T) might be susceptibility to myocardial infarction in a north Indian population." (PMID 26537097, 2015). "A pilot study in a north Indian population suggested that APOA1 polymorphisms (-75 G/A and +83 C/T) might be susceptibility to myocardial infarction." (PMID 26173491, 2015). "A pilot study in a north Indian population suggested that the ApoA1 -75 G allele might be a susceptibility allele for myocardial infarction." (PMID 24885977, 2014). "A pilot study in a north Indian population suggested that the APOA1 -75 G allele might be susceptibility alleles for myocardial infarction." (PMID 24209603, 2013).
myocardial infarction (continued). "In addition, according to a large comprehensive study (INTERHEART study) the ApoB/ApoA1 ratio was superior for the estimation of the risk of acute myocardial infarction in all ethnic groups, in both sexes and all ages." (PMID 21692678, 2011). "Thus, prothrombotic gene variants and APOA1 rs5069 polymorphism may serve as predictors of early myocardial infarctions." (PMID 39295604, 2024). "Therefore, prothrombotic gene variants and APOA1 rs5069 polymorphism could serve as predictors of early myocardial infarctions, and individuals with early family histories could be screened for these mutations." (PMID 39295604, 2024). "The AMORIS study found a strong direct relationship between ApoB and risk of myocardial infarction (MI) and an indirect inverse relationship between ApoA1 and risk of MI." (PMID 35295919, 2022). "CSL-112, a r-HDL particle that promotes the formation of small and lipid-poor APOA1 particles, is being tested in a large, randomized study to determine if it reduces the risk of CVD events in patients after myocardial infarction." (PMID 38018436, 2024). "A multinational case-control investigation on acute myocardial infarction (AMI) patients determined that the ApoB/ApoA1 ratio surpasses all cholesterol ratios in assessing AMI risk across varied gender, age, and race demographics." (PMID 38310324, 2024). "There is currently a phase 3 trial underway assessing the potential of recombinant ApoA1 in reconstituted HDL (CSL112) as a therapeutic strategy for preventing early recurrent cardiovascular events after a myocardial infarction." (PMID 38052254, 2024). "The INTERHEART study has investigated the Apolipoprotein B (ApoB)/ Apolipoprotein A1 (ApoA1) and TC/HDL-C ratios finding an association with acute myocardial infarction (AMI) more frequently in women than in men." (PMID 35268267, 2022). "ApoA1-treated rats in vivo showed a significant reduction in myocardial infarct size along with an increase in phosphorylation and activation of RISK and SAFE signaling, including Erk1/2, Akt, and GSK3β." (PMID 34956045, 2021). "The INTERHEART study suggested that ApoB/apoA1 ratio provided the greatest odds ratio for myocardial infarction (OR = 1.59, 95% CI 1.52–1.64, 3]." (PMID 31744496, 2019). "For example, it would be interesting to determine the role of ApoA1 degradation by chymase, in the context of myocardial infarction." (PMID 30233357, 2018). "ApoB/ApoA1 ratio was recommended as an accountable risk marker of acute myocardial infarction, unlike the TC/HDLc ratio." (PMID 33725226, 2021). "Recent studies from our group have shown that elevated serum levels of ApoA-1 antibodies (anti-apoA-1 IgG) can predict unfavourable cardiovascular events in patients with myocardial infarction (MI), severe carotid stenosis, rheumatoid arthritis (RA), and also in the general population." (PMID 33086507, 2020). "Analyses between tertiles showed a significant difference for the history of myocardial infarction (MI), which was most common in patients with the highest levels of anti-apoA-1 IgG (p = 0.047), as well as for diabetic nephropathy (p = 0.04) as the primary renal disease." (PMID 31261925, 2019). "In addition, an apoB/apoA1 ratio of more than 0.7 in men and 0.6 in women was indicated by Walldius as a signal of subsequent occurrence of myocardial infarction." (PMID 24886173, 2014). "A number of prospective studies have shown that high apoB/apoA1 ratio may be a promising marker for predicting the occurrence of future cardiovascular events, such as myocardial infarction and stroke." (PMID 24886173, 2014). "Moreover, the ApoB/ApoA1 ratio is a better predictor of lipoprotein-related risk of cardiovascular disease (CVD) than traditional lipid indexes, and ApoB and ApoA1 are correlated with creatine kinase (CK) in myocardial infarction." (PMID 35069437, 2021).
myocardial infarction (continued). "In the second part of the study, the aim was to determine the association of nonsynonymous (NS) and synonymous (S) variants in APOA1 in the general population with plasma levels of apoA-I and HDL cholesterol, and with risk of myocardial infarction (MI)." (PMID 23209431, 2012). "Meanwhile, the ApoA-I Event Reducing in Ischemic syndromes I (AEGIS-I) trial used infusions of CSL112, a reconstituted plasma-derived apoA-1, in patients with acute myocardial infarction." (PMID 33260660, 2020). "Meanwhile, the levels of ApoA1 and HDL in patients with myocardial infarction were significantly lower than those in the control group, and the levels of both increased significantly with age (27737874)." (PMID 30681575, 2019). "A previous study indicated that a high apoB/apoA1 ratio and high non-HDL-C levels are significantly correlated with in-hospital MACEs and out-of-hospital adverse endpoints, including angina, myocardial infarction, new-onset heart failure, stroke, and cardiac death." (PMID 32219140, 2020).
type 2 diabetes (112 papers, 2008 to 2026). "Type 2 diabetes liability and fasting insulin were inversely associated with apolipoprotein A1, total cholines, lipoprotein subfractions in high-density-lipoprotein and intermediate-density lipoproteins, and positively associated with aromatic amino acids." (PMID 38459184, 2024). "The apoB/apoA-1 ratio already about 20 years in advance is associated with development of type 2 diabetes, as seen in the AMORIS cohort." (PMID 34851955, 2021). "The presence of anti-apoA-1 autoantibodies is also a risk biomarker for cardiovascular disease in type 2 diabetes mellitus, which is increased in HCV infection." (PMID 29423541, 2018). "APOA1, a protein with multiple therapeutic functions, has been reported to be associated with an improved glycaemic control in patients with type 2 diabetes and a decelerated progression of prediabetes to type 2 diabetes." (PMID 36414942, 2022). "Epidemiological studies have also demonstrated that apolipoproteins and the apoB/apoA1 ratio represent potential risk factors for the development of type 2 diabetes mellitus (T2DM), insulin resistance, non-alcoholic fatty liver disease, metabolic syndrome, and cancer." (PMID 29312456, 2018). "In terms of CVD risk factors, BMI, dyslipidaemia and Type II diabetes mellitus (T2DM) were reported to positively associate with ApoB and ApoB: ApoA1 and negatively with ApoA1 among adolescents from Brazil and adults from China." (PMID 40375303, 2025). "Recent studies have suggested that, beyond traditional lipid parameters, apolipoprotein A1 (ApoA1), apolipoprotein B (ApoB), and lipid ratios are particularly relevant in patients with type 2 diabetes." (PMID 41322311, 2025). "Previous studies have reported a decrease of PON1 activity and of apoA-1 levels in type-2 diabetes (T2D)." (PMID 35883764, 2022). "This is in contradiction with previous findings reporting a significant increase in apoA1 concentration in subjects with type 2 diabetics who had consumed 200 g of raw tomatoes daily for 8 weeks." (PMID 35978954, 2022). "ApoA1, ApoB, and the ApoB/A1 ratio have been suggested as early indicators for predicting type II diabetes." (PMID 36329547, 2022). "In a previous study, we found elevation of lipids, lipoproteins, and the apoB/apoA-1 ratio to be present about 15 years before diagnosis of type 2 diabetes." (PMID 30138379, 2018). "In a recent study in type 2 diabetes the incidence of autoantibodies to apoA-1 was 37.5% in patients with cardiovascular disease (CVD) and patients who were autoantibody positive showed 5.7 times increased CVD risk." (PMID 29423541, 2018). "Median serum levels of CRP, triacylglycerol, plasma glucose and HOMA-IR were higher among those who developed type 2 diabetes, whereas ApoA-1 levels were lower." (PMID 28612106, 2017). "On the other hand, Framingham score increased with age, type 2 diabetes, and ApoB and it decreased with ApoA1, large HDL and Intermediate HDL." (PMID 25015177, 2014). "In addition, it was found that low levels of APOA1 can be used to differentiate type 2 diabetes secondary to pancreatic cancer from common type 2 diabetes mellitus." (PMID 38067270, 2023). "In type 2 diabetes subjects, tomato juice consumption decreased susceptibility of LDL to oxidation, and daily consumption of 200 g raw tomato for 8 weeks decreased both systolic and diastolic blood pressure and increased ApoA1 plasma concentrations." (PMID 32517202, 2020). "The intake of RJ possesses enviable response on serum glucose, apolipoprotein A1 (ApoA-1) concentrations, and (ApoB/ApoA-1) ratios that may decrease cardiovascular attack in people with type-2 diabetes." (PMID 31936187, 2020). "Moreover, the APOA1/HDL cholesterol ratio was the strongest predictor of incident type 2 diabetes, and APOB level is significantly correlated with plasma insulin level in women." (PMID 28549478, 2017). "High concentrations of ApoA1 were found to be predictive of type-2 diabetes in Turkish adults." (PMID 24093822, 2013).
type 2 diabetes (continued). "However, it was recently demonstrated that high ApoA1 levels could predict the development of prehypertension and type-2 diabetes." (PMID 25849372, 2015). "The ratio of LDL-C/HDL-C, ApoB/ApoA1, ApoB/LDL-C and ApoA1/HDL-C and other variables were analyzed to determine their potential roles in type 2 diabetes in the Taiwanese population." (PMID 24093822, 2013). "The group with Type 2 diabetes had higher body mass index (BMI), while the group with CHD had lower HDL cholesterol and apoA1." (PMID 18937674, 2008). "This trend has been observed in a previous study examining anti-apoA-1 in type 2 diabetes, and although our study was not exclusively in patients with type 2 diabetes, more than half the participants had a history of it." (PMID 34888742, 2022). "For example, HDL from type 2 diabetes (T2D) patients contains ApoA1 and ApoA2 proteins that are modified by non-enzymatic glycation." (PMID 34638523, 2021). "In patients with type 2 diabetes, B1B1 homozygotes compared with B2 carriers (B1B2 + B2B2) had a significant decrease in apoB levels (-19.05 ± 6.12 mg/dL) and apoB: apoA-1 ratio (-0.12 ± 0.04) and an increase in Lp(a) levels (6.37 ± 2.17 mg/dL) following the intake of sesame-canola oil." (PMID 33123324, 2020). "Associations of apoA1 in HDL that contained or lacked apoC3 each with liver fat content were not modified by age, sex, race, or type 2 diabetes status (all Pinteraction > 0.05)." (PMID 33142714, 2020). "In patients with type 2 diabetes, we found generally a significant genotype effect; such that individuals with B1B1 genotype showed a significant decrease in apoB, apoB: apoA-1, insulin, and HOMA-IR and also an increase in QUICKI compared with B2B2 homozygotes." (PMID 33123324, 2020).